LOX (lysyl oxidase)
Diseases named in the same sentence as LOX in open-access papers (continued):
Sharing a sentence is not in itself a finding about the gene and the disease.
colon carcinoma (31 papers, 2011 to 2024). "Intracellular LOX is significantly associated with poor survival and a prognostic biomarker for lung/hepatic metastasis of colon cancer." (PMID 34502094, 2021). "Results indicated that the LOX G473A SNP increases the risk of lung, and colorectal (colon and rectum) cancers in humans, and also enhances the susceptibility of humans to cigarette smoking eliciting lung and colon cancers." (PMID 27367711, 2016). "LOX expression has been found to be elevated in a variety of cancers, including breast, prostate, lung, and colon cancer." (PMID 38694111, 2024). "The positive correlation between CD68 and HIF1A, and the increased CA9 and LOX expression in CD68HighHIF1AHigh patients were validated on the Oncomine database (colon cancer Bittner cohort, with the highest number of patients)." (PMID 32231135, 2020). "In colon cancer, LOX enzymatic activity was shown to drive cancer cells proliferation and invasion through SRC activation mediated by β3 and β4 integrins." (PMID 31130685, 2019). "Here for the first time, our results demonstrated the existence of LOX proenzyme (50kDa) and mature enzyme (32kDa) within the nuclei of colon cancer cells." (PMID 28947950, 2017). "A direct relationship between LOX enzymatic activity and tissue stiffness has also been reported in colon cancer." (PMID 28423580, 2017). "We also charactersied the expression and localisation of LOX in three well-known colon cancer cell lines." (PMID 28947950, 2017). "From this hypoxia signature, we selected LOX for further analysis given we wished to investigate factors that could modulate the stroma that are targetable, its previous association with the mesenchymal subtype and reports of its involvement in metastasis in breast and colon cancer." (PMID 26077591, 2015). "For example, in a colon cancer study, 5-LOX expression was found to be positively correlated with polyp size, intraepithelial neoplasia and adenoma, suggesting that LOX may contribute to the early stage of colon cancer." (PMID 35158821, 2022). "Moreover, targeting β1 integrin was shown to be ineffective against LOX-driven proliferation of colon cancer cells, whereas β3 and β4 blocking was effective." (PMID 31130685, 2019). "Furthermore, we are the first to identify LOX enzyme isoforms (50 kDa and 32 kDa) within the nucleus of colon cancer cell lines by confocal microscopy and Western blot." (PMID 28947950, 2017). "In support of this, we also observed elevated LOX expression in the nucleus of the metastatic colon cancer cell line (SW620), a cell line derived from a lymph node metastases taken from the same patient as the isogenically matched non-metastatic colon cancer cell line (SW480)." (PMID 28947950, 2017). "Our observations obtained by immunohistochemistry on human tissues point out that LOX-1 protein expression is modulated in colon tumorigenesis, in fact we find a strong up-regulation of LOX-1expression in colon cancer tissues, as compared to healthy counterpart of the same patients." (PMID 26895376, 2016). "Indeed, we previously showed that LOX signals through SRC to increase colon cancer tumor cell proliferation, invasion and metastasis." (PMID 26077591, 2015). "There is a well-established link between hypoxia and upregulation of LOX expression, which only reinforces this situation and further impedes drug access to tumors, although it has also previously been shown that LOX activity can stimulate angiogenesis in colon cancer." (PMID 26077591, 2015). "Moreover, LOX itself was discussed to possess a role in both effects in colon cancer." (PMID 26265048, 2015). "High expression of Tspan8 was restricted to the colon carcinoma cell line HT29, while low to medium expression was detectable in IGROV-1, LOX and Huh7, reflecting the cancer genome data." (PMID 36078095, 2022).
colon carcinoma (continued). "Furthermore, since both the LOX and COX pathways were implicated in the development of precancerous colonic polyps, the use of such broad-spectrum LOX and COX inhibitors together with the activation of 15-LOX may be valuable in the chemoprevention of colitis-associated colon cancer." (PMID 29710854, 2018). "In addition, LOX is involved in the hypoxic upregulation of HIF-1α, while LOX and HIF-1α potentiate each other to foster colon tumor progression through the PI3K/Akt signaling pathway." (PMID 34815382, 2021). "When exploring tumor databases, we demonstrated that colon tumors exhibit distinct levels of macrophage infiltration, where the most infiltrated tumors are also the most hypoxic ones, presenting higher levels of HIF1A, CA9, and LOX expression." (PMID 32231135, 2020). "Conversely, experiments using SW480, a non-metastatic colon cancer cell line with low LOX expression, showed that overexpression or systemic delivery of LOX leads to bone metastasis formation." (PMID 30423905, 2018). "Interestingly, lower expression of a number of genes (GREM1, LOX, TNFAIP6, CD36, and EDNRA) predicted better prognosis in both ovarian and colon cancers." (PMID 23536776, 2013).
glioblastoma (28 papers, 2014 to 2025). The most malignant astrocytic tumor (WHO grade IV). "A new study on the effect of PTEN deletion on glioblastoma demonstrated increased infiltration of macrophages via the YES-associated protein 1-Lysyl oxidase b1(LOX-b1) -integrin-PYK2 axis." (PMID 39206155, 2024). "Growing evidence indicated that LOX promotes tumor formation and progression, such as glioblastoma multiforme, hepatocellular carcinoma, etc.; in these studies, the overexpression of LOX is associated with tumor malignancy and poor prognosis." (PMID 36090891, 2022). "Glioblastoma with a mutation in IDH1 expressed lower levels of LOX in the nucleus, and IDH1-mutated cases showed lower LOX expression levels when compared to wild-type IDH1 cases." (PMID 25790191, 2015). "Similarly, PTEN deficiency in glioblastoma cells activates Yap1, which upregulates Lysyl Oxidase (LOX) expression, attracting macrophages to the tumor microenvironment via the β1 integrin-PYK2 (protein tyrosine kinase 2-beta) pathway." (PMID 40057606, 2025). "To investigate the impact of the LOX family on glioblastoma, we analyzed the expression of LOX family members (LOX, LOXL1, LOXL2, LOXL3, and LOXL4) in normal human astrocytes (Heb) and glioblastoma cell lines (T98G and LN-229)." (PMID 40270974, 2025). "To investigate LOX’s impact on glioblastoma’s clinical features, we analyzed the clinical and pathological characteristics of glioblastoma cases with varying expressions of the LOX family." (PMID 40270974, 2025). "In the context of glioblastoma, we have shown that YAP1 is essential for PTEN deficiency-induced transcriptional upregulation of LOX, which, in turn, triggers macrophage infiltration into the TME3." (PMID 38443336, 2024). "We also confirmed hypoxia induced LOX in U87 human glioblastoma cells 35, and we show that LOX is hypoxia-induced in human pancreatic fibroblasts." (PMID 37848450, 2023). "We confirmed that HSPA7 promoted macrophage infiltration and SPP1 expression via upregulating the YAP1 and LOX expression of glioblastoma stem cells (GSCs) in vitro and in our clinical GBM tumor samples." (PMID 34354698, 2021). "LOX activities have also been recognized in glioblastoma, diabetic neovascularization, osteogenic differentiation, bone matrix formation, ligament remodeling, polycystic ovary syndrome, fetal membrane rupture and tumor progression and metastasis." (PMID 32708046, 2020). "Glioblastoma cells secrete, in vitro and under hypoxic conditions, exosomes that contain protein-lysine 6-oxidase (LOX), thrombospondin-1 (TSP1), vascular endothelial growth factor (VEGF) and metalloproteinase with thrombospondin motifs 1 (ADAMTS1)." (PMID 32824183, 2020). "Clearly, cells expressing IRE1α RNase mutants heightened the expression of ECM markers characteristic of glioblastoma malignancy or invasion, including fibrillar collagens, the collagen cross-linker LOX and the proteins THBS1, YKL-40, DCN and LAMA4." (PMID 26325176, 2015). "The expression levels of LOX, BMP1 and HIF1A were correlated and analyzed according to IDH1 mutation status and to the clinical end-point of overall survival of glioblastoma patients." (PMID 25790191, 2015). "Notably, simultaneous targeting of LOX and CLOCK pathways effectively interrupted macrophage and microglial infiltration in PTEN-deficient glioblastoma, markedly enhancing anti-tumor immune responses." (PMID 40076738, 2025). "Specific binding of YAP1 and H3K27ac to the LOX promoter was confirmed in glioblastoma cell models." (PMID 32708046, 2020). "Furthermore, SRC/AKT/YAP1 and YAP1/LOX signaling were shown to positively correlate with macrophage density and reduced overall survival in glioblastoma multiforme patients." (PMID 32708046, 2020). "HSPA7 was found to promote macrophage infiltration and SPP1 expression by upregulating YAP1 and LOX in glioblastoma stem cells (GSCs), both in vitro and in clinical GBM tumor samples." (PMID 39199429, 2024).
glioblastoma (continued). "LOXL1 correlations were detected in LGG with IDH mutation (IDHmut), LOXL3 correlations in LGG with IDH wild type (IDHwt) and strong LOX correlations in glioblastoma (GBM) were found." (PMID 36076905, 2022). "This macrophage infiltration promotes glioma survival and angiogenesis, with LOX inhibition suppressing tumor progression and macrophage infiltration in PTEN-null glioblastoma multiforme (GBM) models." (PMID 40057606, 2025). "This study developed a prognostic signature using hypoxia-related differentially expressed genes (DEGs) in Glioblastoma Multiforme (GBM) and identified three optimal gene signatures (CP, IGFBP2, and LOX) using multi-omics analysis." (PMID 38339384, 2024). "Exosomes released from hypoxic U87MG glioblastoma cells contain an elevated level of some proteins like thrombospondin-1 (TSP1), VEGF, and protein-lysine 6-oxidase (LOX) that promote growth, metastasis, and angiogenesis of tumor." (PMID 33302971, 2020). "LOX functional analyses were performed using siRNA knockdown and the specific inhibitor BAPN in two glioblastoma cell lines." (PMID 25790191, 2015). "LOX influences macrophage infiltration through NF-κB-PATZ1 signaling, while CLOCK modulates microglial recruitment via the OLFML3 axis, both contributing to immune suppression in glioblastoma." (PMID 40076738, 2025). "Selective elevation of lysyl oxidase (LOX), thrombospondin-1(TSP1), VEGF, and ADAM Metallopeptidase With Thrombospondin Type 1 Motif 1(ADAMTS1) in hypoxic exosomes in glioblastoma cells; these exosomes exhibited increased angiogenesis-related parameters compared to those exhibited under normoxia." (PMID 40534881, 2025). "EVs derived from glioblastoma and grown in specifically from hypoxic environment, carry number of proangiogenic cytokines and growth factors and stimulate angiogenesis via modulation of HIF, MMP 9 and LOX." (PMID 31921855, 2019).
ovarian carcinoma (28 papers, 2013 to 2025). A malignant neoplasm originating from the surface ovarian epithelium. "In patients with the lysyl oxidase G473A (rs1800449) polymorphism, the A allele is associated with an increased risk of ovarian cancer in the population of Eastern India." (PMID 35054220, 2021). "A comparison of the serum LOX levels of A alleles showed significantly high (p < 0.05) levels in ovarian cancer cases (4.31 ± 1.12) as compared to control (1.62 ± 0.48)." (PMID 35054220, 2021). "Extended studies with a larger sample size would further substantiate the association of LOX gene polymorphisms with disease progression in ovarian cancer." (PMID 35054220, 2021). "This preliminary study provides a snapshot of the association between LOX G473A polymorphism with risk of ovarian cancer and the role of serum LOX in diagnosis." (PMID 35054220, 2021). "A allele was predominant among the cases, suggesting the association of LOX G473A polymorphism as a risk factor in ovarian cancer." (PMID 35054220, 2021). "It has also been reported that LOX G473A polymorphism acts as tumor promoter in ovarian cancer cells." (PMID 35054220, 2021). "In the present study, the frequency of the LOX G473A polymorphism, the AA genotype was found significantly higher in ovarian cancer patients as compared to control subjects." (PMID 35054220, 2021). "Further, a polymorphism at G473A of LOX was shown to be associated with ovarian cancer in the Han Chinese population." (PMID 35054220, 2021). "The present study evaluated the pattern of LOX G473A polymorphism (rs1800449) and serum LOX levels in ovarian cancer patients." (PMID 35054220, 2021). "A collagen-remodelling gene signature containing COL1A1 and LOX is associated with the progression of ovarian cancer and unfavourable patient survival." (PMID 35004308, 2021). "LOX expression was also associated with progression, invasion, and drug resistance in breast, colorectal, and ovarian cancer patients." (PMID 30583585, 2018). "In this study, first, the association between hypoxia and increased LOX expression was validated in clinically relevant ovarian cancer paraffin-embedded tissues by immunohistochemical method." (PMID 23545606, 2013). "To determine if this observed limited invasive capacity resulted from decreased extracellular matrix remodeling activity, as a proof-of-concept we next determined MMP2 and LOX protein expression in drug-treated spheroids since these proteins are associated with ovarian cancers’ invasive capacity." (PMID 36727073, 2022). "The serum LOX level of A alleles was found to be significantly higher in ovarian cancer cases as compared to control, pointing towards the fact that active LOX, cleaved from the pro-enzyme in the extra-cellular environment, is able to re-enter the cells, thereby influencing the serum LOX levels." (PMID 35054220, 2021). "Wu et al21 illustrated that the rs1800449 G473A polymorphism of LOX might increase the susceptibility and recurrence of ovarian carcinoma." (PMID 33058284, 2020). "Therefore, we hypothesize that expression of LOX and collagens in ovarian cancer tissues may be associated with drug resistance since LOX is responsible for the collagen cross-linking increasing ECM stiffness." (PMID 30583585, 2018). "The expression of LOX proteins has been shown to correlate with poor clinical outcomes in several cancers, such as breast, prostate, and ovarian cancers." (PMID 40661776, 2025). "Hypoxia has also been shown to upregulate LOX expression thereby promoting invasion and metastasis of breast and ovarian cancer cell lines." (PMID 38016355, 2024). "In ovarian cancer, LOX functions as tumour progressor and positively regulates in metastatic cascade." (PMID 35054220, 2021). "Further functional studies related to tissue expression, local niche, activation of functional LOX from its precursor proenzyme form, and its release into circulation, would provide an insight into the genotype–phenotype link in ovarian cancer patients." (PMID 35054220, 2021).
ovarian carcinoma (continued). "Serum LOX level in early-stage ovarian cancer was significantly lower as compared to advanced stage (FIGO stage III & IV)." (PMID 35054220, 2021). "Second, signatures increased in collagen expression together with LOX, THBS2, TIMP3 and SPARC have also been associated with decreased survival in ovarian cancer." (PMID 33379263, 2020). "In high-grade serous ovarian cancer (HGSOC), hypoxic signaling increases the expression of lysyl oxidase (LOX) in mesothelial and ovarian cancer cells to promote collagen crosslinking and tumor cell invasion." (PMID 33324550, 2020). "A recent report has also identified LOX as a druggable molecular target which drives collagen remodeling and metastatic progression in ovarian cancer, further supporting the notion to develop selective LOX inhibitors." (PMID 31130685, 2019). "We analyzed the migratory abilities of ovarian cancer cells through Transwell chamber analysis in control or LOX silenced OV56 cells transfected with miR-508-3p inhibitor or control or LOX-overexpressing COV504 cells transfected with miR-508-3p mimic." (PMID 30478449, 2019). "On the other hand, the high expression of LOX was described as the metastasis promoter in lung adenocarcinoma, breast, colorectal, and ovarian cancer." (PMID 30583585, 2018). "This represents the study where molecules related with CSCs (ALDH1A1) and ECM (LOX, collagens) models of drug resistance are described as occurring simultaneously in ovarian cancer cells treated with PAC and TOP." (PMID 30583585, 2018). "We then verified 10 selected genes in the independent set of ovarian cancer samples (test set) and found LOX and DSPG3 to be significant." (PMID 27028324, 2016). "In summary, two genes—i.e., DSPG3 and LOX—were significantly associated with OS and DFS in the learning and test sets of ovarian cancer samples." (PMID 27028324, 2016). "These novel findings validate the role of LOX in ovarian cancer metastasis and indicate the importance of reoxygenation when studying hypoxia induced phenomena." (PMID 23545606, 2013). "Further studies are needed to clarify the relationship between PI3K/AKT and other pathways in LOX signaling of ovarian cancer cells." (PMID 23545606, 2013). "We report the relationship between hypoxia/reoxygenation, LOX catalytic activity, and LOX-induced migration in the ovarian cancer cells HO8910 and HO8910-PM." (PMID 23545606, 2013). "Ovarian cancer cell migration and invasion capability decrease markedly after LOX siRNA transfection under both normoxia and hypoxia conditions." (PMID 23545606, 2013). "LOX and HIF-1α proteins are both overexpressed in ovarian cancer cells and the expression is significantly associated with advanced clinical stages and metastasis in EOC." (PMID 23545606, 2013). "Our data suggest that LOX is involved in ovarian cancer cell migration and invasion capability regulation and is related to HIFs." (PMID 23545606, 2013). "Transwell migration assay and cell invasion assay, together with LOX siRNA transfection method were performed to study the effect of LOX on ovarian cancer cell migration and invasion capability." (PMID 23545606, 2013). "This study investigated the role of LOX in promoting invasion and metastasis of epithelial ovarian cancer in a hypoxic environment and its specific signal transduction pathway." (PMID 23545606, 2013). "Our data suggest that LOX likely regulates various types of ovarian cancer cells through different signaling pathways." (PMID 23545606, 2013). "We found that HIF-1α and LOX are highly expressed in epithelial ovarian cancer tissues, and the expression of both proteins is significantly correlated with the tumor grade, tumor diameter and lymph node metastasis." (PMID 23545606, 2013). "Although LOX has been shown to play roles in tumor metastasis, the mechanism by which LOX expres sion is upregulated in ovarian cancer cells and the correlation with hypoxia are still poorly understood." (PMID 23545606, 2013).